MMP2 (matrix metallopeptidase 2)
Diseases named in the same sentence as MMP2 in open-access papers (continued):
Sharing a sentence is not in itself a finding about the gene and the disease.
endotoxemia (5 papers, 2010 to 2022). "These authors suggest that the increase in plasma MMP-2 activity is related to endotoxemia, and that the increase in urinary MMP-9 complex and pro-MMP-9 activities is indicative of AKI." (PMID 36230418, 2022). "In the current study, therefore, using an animal model of endotoxemia, role of MMP-2 and MMP-9 in mediating LPS-induced degradation of ZO-1 and syndecan-1 was investigated." (PMID 26199464, 2015). "In an ovine model of septic cardiac failure, MMP-2 levels were shown to be even higher in noradrenaline-masked hypovolemia added to endotoxemia than in endotoxemia alone." (PMID 20356362, 2010). "Taken together, LPS induced significant upregulation and activation of MMP-2 and MMP-9 in the rat endotoxemia model, which may contribute to the development of vascular leaking through shedding endothelial surface glycocalyx complex." (PMID 26199464, 2015). "Dexamethasone and doxycycline may protect endothelial cells from injury and glycocalyx from shedding through suppressing MMP-2 and MMP-9 in LPS-induced rat endotoxemia model." (PMID 26199464, 2015).
Granuloma (5 papers, 2012 to 2022). A compact, organized collection of mature mononuclear phagocytes, which may be but is not necessarily accompanied by accessory features such as necrosis. "Additionally, tissue localization of MMP-9 and MMP-2 was confirmed in apical granulomas by imunohistochemistry." (PMID 22436166, 2012). "In this study, we examined existing human TB granuloma datasets in combination with infectious and non-infectious granuloma models to probe the increased expression of MMP-2 and MMP-9 in Mtb granulomas." (PMID 29698476, 2018). "This supports the demonstration that myofibroblasts isolated from granuloma tissue express MMP-9 but not MMP-2, which was found to be produced by other cell types." (PMID 23840855, 2013). "Thus, it can be concluded that the observed elevation in MMP-2 and the decline in TIMP-2 expression may have contributed to collagen degradation and a consequent decrease in granuloma diameters and fibrotic areas following TELM treatment." (PMID 23829789, 2013). "To examine the induction and expression of MMP-2 and MMP-9 in experimental infectious and non-infectious murine TB granuloma models we used both a subcutaneous granuloma model for in vivo imaging in parallel with the more conventional, intranasal Mtb challenge." (PMID 29698476, 2018).
hematoma (5 papers, 2015 to 2026). A hematoma is a collection of blood from a vascular structure into an extravascular space. "This is the first study proposing that MMP-2 and TIMP-2 genotypes are associated with the SDICH susceptibility and hematoma size with age and gender difference." (PMID 26551785, 2015). "This study aimed to discuss relationship of MMP-2 and TIMP-2 to spontaneous deep ICH (SDICH) susceptibility and hematoma size." (PMID 26551785, 2015). "Some investigators have provided explicit evidence that the concentrations of MMP-2 and MMP-9 are significantly elevated in hematoma fluid, indicating that the MMP/VEGF system may be involved in the angiogenesis associated with CSDH." (PMID 35207175, 2022).
hypopharyngeal carcinoma (5 papers, 2018 to 2023). Carcinoma, predominantly squamous cell, arising from the epithelial cells of the hypopharynx. "Zhe Song found a positive association of lymph nodes metastasis and the degree of lymphatic metastasis with the expression intensity of MMP-2 in hypopharyngeal carcinoma." (PMID 36639546, 2023). "The anti-migratory efficacy of α-TOS is corroborated in hypopharynx carcinoma cells by decreasing the secretion of matrix metalloproteases 2 and 9 (MMP-2 and MMP-9) and inhibiting cell migration." (PMID 30235821, 2018). "The expression of MMP-2 and MMP-9 in hypopharyngeal carcinoma was significantly higher than that in pericarcinoma tissue, and it was enhanced with the increase of clinical stage." (PMID 31882379, 2021). "The results showed that the protein expression levels of MMP-2 and MMP-9 was consistent with the mRNA expression in hypopharyngeal carcinoma and pericarcinoma tissues." (PMID 31882379, 2021). "In hypopharyngeal cancer tissues, mRNA and protein levels of MMP-9 and MMP-2 are significantly upregulated compared to paracancerous tissues." (PMID 32961679, 2020). "Moreover, the expression levels are enhanced with the increased lymph node metastasis degree and tumor clinical stages, suggesting that MMP-2 and MMP-9 are involved in the occurrence and aggressiveness of hypopharyngeal cancer." (PMID 32961679, 2020). "Thus, MMP-2 and MMP-9 may be involved in the occurrence, development, invasion and metastasis of hypopharyngeal carcinoma through a variety of mechanisms." (PMID 31882379, 2021).
inflammatory breast carcinoma (5 papers, 2013 to 2024). An advanced, invasive breast adenocarcinoma characterized by the presence of distinct changes in the overlying skin. "A previous study demonstrated that a higher serum level of MMP-2 was correlated with favorable outcome in inflammatory breast cancer treated with bevacizumab-based chemotherapy." (PMID 29949618, 2018). "This analysis performed in the BEVERLY-2 phase II trial identified MMP2 and MMP9 as candidate biomarkers correlated consistently to DFS and OS in patients with HER2-positive inflammatory breast cancer." (PMID 26921265, 2016).
ischemia reperfusion injury (5 papers, 2011 to 2023). Adverse functional, metabolic, or structural changes in ischemic tissues resulting from the restoration of blood flow to the tissue (reperfusion), including swelling; hemorrhage; necrosis; and damage from free radicals. "MMP-2-neutralizing antibodies have shown protective effects in hearts exposed to ischemia-reperfusion injury." (PMID 21815879, 2011). "The present study investigated whether Rho-associated protein kinase (RhoA/ROCK) signaling pathway inhibitor simvastatin inhibits matrix metalloproteinase 2 (MMP-2) activity in a rat ischemia-reperfusion injury (I/Ri) model by inhibiting the RhoA/ROCK pathway and reducing MMP-2 mRNA levels." (PMID 36139129, 2022). "In addition, several studies demonstrated that doxycycline and minocycline inhibited MMP-2 and MMP-9 expression in animal models of ischemia reperfusion injury and thereby reduced the pathology." (PMID 28257106, 2017).
leprosy (5 papers, 2018 to 2022). Leprosy is a chronic infectious disease affecting primarily the skin and peripheral nervous system. "Increased MMP-2, MMP-9 mRNA, and protein MMP-9 levels were detected together with enhanced TNF-α and IFN-γ expression levels in the lesions of both tuberculoid patients and in those undergoing leprosy reactions like ENL." (PMID 34692720, 2021).
liposarcoma (5 papers, 2013 to 2024). A usually painless malignant tumor that arises from adipose tissue. "In synovial sarcoma and liposarcoma, enhanced MMP2 protein also correlates with poor disease-free survival and in liposarcoma it correlates with both tumor grade and metastasis." (PMID 31466240, 2019). "Furthermore, cells in our 3D model showed an induction of specific biomarkers associated with liposarcoma pathogenesis, e.g. β-catenin and E-cadherin, and aggressiveness, e.g. ALDH1, MMP2, MMP9 and Slug." (PMID 27895047, 2017). "In liposarcoma cells, TNF-α strongly stimulated MMP-9 and showed slight up and down activity on MMP-2." (PMID 24085323, 2013).
lupus nephritis (5 papers, 2012 to 2023). Glomerulonephritis in the context of systemic lupus erythematosus. "The MMP2 and MMP9 mRNA levels were significantly up-regulated in class IV lupus nephritis." (PMID 22479529, 2012). "In sum, the vector that point at chromatin-IgG deposits in GBM are clustered with vectors pointing at TLR7–9, Clec4e, MMP2 and MMP9, indicating an interdependency between them, while the DNaseI vector points the opposite direction due to its negative correlation with advanced lupus nephritis." (PMID 22479529, 2012).
malignant mesothelioma (5 papers, 2012 to 2023). A malignant neoplasm of the pleura or peritoneum, arising from mesothelial cells. "Another study indicated that downregulation of CBX6 induced MMP-2 expression and an invasive phenotype in malignant mesothelioma cells." (PMID 36140750, 2022). "Active MMP-2 level was significantly elevated in malignant mesothelioma compared to uninflamed pleura, and this was correlated to poor prognosis." (PMID 33028834, 2020). "Matrix metalloproteinases (MMPs) secreted by malignant mesothelioma, especially MMP2, play crucial roles in tumor invasion and metastasis." (PMID 22737246, 2012).
mammary adenocarcinoma (5 papers, 2002 to 2023). "Furthermore, NO promotes tumour cell invasion in the C3L5 murine mammary adenocarcinoma model by altering the balance between the expression of matrix metalloproteinase-2 (MMP-2) and it's tissue inhibitors-2 and -3 (TIMP 2 and TIMP 3)." (PMID 11953890, 2002). "On the contrary, inhibition of ERK signalling pathway might result in decreased expression of MMP‐2 and MMP‐9 in human breast adenocarcinoma cells." (PMID 27491646, 2017).
muscular dystrophy (5 papers, 2007 to 2025). Muscular dystrophy (MD) refers to a group of more than 30 genetic diseases characterized by progressive weakness and degeneration of the skeletal muscles that control movement. "Both MMP2 and MMP14 have been shown to promote adipogenesis in adipose tissue, skeletal muscle, and FAPs and are implicated in the pathogenesis of several muscular dystrophies, including Duchenne, Emery-Dreifuss, and congenital muscular dystrophy 1D." (PMID 40966415, 2025). "Under pathological conditions, such as cancer and muscular dystrophies, DG may be the target of metalloproteinases MMP-2 and MMP-9, contributing to disease progression." (PMID 29447293, 2018). "While MMPIs have been found to mitigate disease progression in mouse models, genetic studies have provided evidence that some MMPs (e.g., MMP-2 and MMP-10) may have beneficial roles in muscular dystrophy." (PMID 25364719, 2014). "We hypothesized that MMP-2 and/or MMP-9 might also play an important role in the pathogenesis of muscular dystrophies, involving ECM remodeling during the cycle of muscle fiber degeneration and regeneration." (PMID 17598883, 2007).
neuropathy (5 papers, 2009 to 2024). A disorder affecting the nervous system that manifests with pain, tingling, numbness, and/or muscle weakness. "Therefore, inhibition of MMP-2 may be suggested as a novel treatment for neuropathy." (PMID 38641841, 2024). "Recent studies have shown that other metalloproteinases, MMP2 and MMP9 contribute to the allodynia that follows neuropathy." (PMID 20003309, 2009). "Moreover, the factors associated with DSP signs and symptoms differed in PWH (Factor 2, VCAM-1, and sTNFRII) and PWoH (Factor 4, MMP-2), suggesting that the biological determinants of neuropathy signs and symptoms differ between people with and without HIV." (PMID 38673830, 2024).
pseudoexfoliative glaucoma (5 papers, 2008 to 2025). "The aim of this study was to assess changes in metalloproteinases (MMP-2) and tissue inhibitor of metalloproteinases (TIMP-2) following selective laser trabeculoplasty (SLT) in patients with pseudoexfoliative glaucoma (PEXG)." (PMID 18939999, 2008). "In pseudoexfoliative glaucoma (PEXG), the enzyme balance between MMP-2 and TIMP-2, already impaired by the pseudoexfoliative syndrome (PEX), is seriously altered even compared with POAG." (PMID 18939999, 2008). "Furthermore, in patients with exfoliative glaucoma, the reduction in IOP after SLT correlated with a decrease in the ratio between TIMP2 and MMP2." (PMID 39769228, 2024).
pulpitis (5 papers, 2021 to 2024). Inflammation of the dental pulp. "Our study has shown that the activation of proteolytic enzymes MMP-1 and MMP-2 is increased in acute experimental pulpitis induced by LPS." (PMID 33628825, 2021). "The molecular characterization of proteins in irreversible pulpitis includes MMP-12, MMP-9, RANTES, MIP-2, MCP-1, MMP-2, MMP-1, and P-Selectin, which exhibited correlations of ≥0.8 with the duration of pain caused by cold." (PMID 38279358, 2024). "LPS activates inflammatory cytokines, such as IL‐1, IL‐6, IL‐8, matrix metalloproteinase (MMP)‐9, MMP‐2, and TNF‐α28, 29, 30 in the pulpitis progress." (PMID 35334501, 2022). "Recent studies have shown that MMPs take part in pulpitis, and the levels of MMP-1 and MMP-2 are considerably higher in pathological pulp tissue than in healthy pulp tissue." (PMID 33628825, 2021). "In the present study, MMP-2 and MMP-9 were significantly upregulated in LPS-stimulated hDPCs and further repressed by treatment with S14G-humanin, indicating a potential protective effect of S14G-humanin on the impaired ECM during the progression of pulpitis." (PMID 34605740, 2021).
renovascular hypertension (5 papers, 2014 to 2023). High blood pressure secondary to renal artery stenosis. "Further, increased vascular ROS generation and NF-κB activation also promote MMP-2 activity in rat model of renovascular hypertension." (PMID 25143788, 2014).
silicosis (5 papers, 2015 to 2024). Silicosis is a respiratory disease caused by breathing in (inhaling) silica dust. "In the present study, we showed that the diagnostic value of the serum biomarkers KL-6, SP-D, and MMP-2 was higher in patients with asbestosis or patients with silicosis than in DEWs and HCs." (PMID 29149883, 2017). "To clarify the potential diagnostic biomarkers for asbestosis and silicosis, we measured the serum concentrations of KL-6, SP-D, and MMP-2, -7, and -9 in discriminating patients with asbestosis and silicosis from dust-exposed workers (DEWs) without pneumoconiosis and healthy controls (HCs)." (PMID 29149883, 2017). "The combination of KL-6, SP-D, and MMP-2 may improve the diagnostic sensitivity for asbestosis and silicosis." (PMID 29149883, 2017). "For example, the combined use of KL-6, SP-D and matrix metalloproteinase-2 (MMP-2) for the diagnosis of asbestos and silicosis achieved a sensitivity of 83% and a specificity of 62%." (PMID 39882130, 2024). "KL-6, SP-D, and MMP-2 are available biomarkers for the adjuvant diagnosis of asbestosis and silicosis." (PMID 29149883, 2017). "ROC curve analysis was used to evaluate the ability of the serum KL-6, SP-D, and MMP-2 concentrations to differentiate patients with asbestosis from patients with silicosis, DEWs and HCs or asbestosis and silicosis from DEWs and HCs." (PMID 29149883, 2017). "The order of diagnostic accuracy according to the ROC curve was KL-6, SP-D, and MMP-2 in patients with asbestosis alone and in the combination of both patients with asbestosis and those with silicosis." (PMID 29149883, 2017). "The ROC curve analysis showed that the area under the curve of KL-6 was the largest, indicating that it is more effective than SP-D and MMP-2 in the diagnosis of asbestosis or silicosis." (PMID 29149883, 2017). "The order of diagnostic accuracy according to the ROC curve was KL-6, SP-D, and MMP-2 in patients with asbestosis alone and in patients with asbestosis plus those with silicosis." (PMID 29149883, 2017). "The serum KL-6 and MMP-2 concentrations were highest in patients with asbestosis and second highest in patients with silicosis; these concentrations were significantly different from those in DEWs and HCs (P<0.05)." (PMID 29149883, 2017). "This study showed that KL-6, SP-D, and MMP-2 are readily available biomarkers for the adjuvant diagnosis of asbestosis and silicosis." (PMID 29149883, 2017). "As MMPs play important roles in the pathogenesis of silicosis, we examined the expression of MMP2 and MMP9 in silica-treated MLE-12 cells." (PMID 26340635, 2015). "Also, SiO2 induced macrophage senescence and silicosis in lung tissue, both of which were accompanied by increased fibrosis-associated factors (IL-1β, IL-6, TNF, and TGF-β1) and MMPs (MMP2, MMP9 and MMP12)." (PMID 35959439, 2022). "Compared with healthy controls, silicosis patients had remarkably higher plasma concentrations of matrix metalloproteinase-2 (MMP-2), matrix metalloproteinase-9 (MMP-9), collagen alpha-1(I) protein (COL1A1), and collagen alpha-1(III) protein (COL3A1) (all p < 0.05)." (PMID 30558126, 2018). "Therefore, the combination of KL-6, SP-D, and MMP-2 can improve the sensitivity of diagnosis of asbestosis and silicosis." (PMID 29149883, 2017). "The area under the curve (AUC) for KL-6 was larger than that for SP-D and MMP-2, indicating that the order of diagnostic accuracy by the ROC curve was KL-6, SP-D, and MMP-2 in patients with asbestosis alone or in both patients with asbestosis and those with silicosis." (PMID 29149883, 2017). "The serum concentrations of KL-6, SP-D, and MMP-2 were not significantly different among the various stages of silicosis." (PMID 29149883, 2017).
systolic heart failure (5 papers, 2012 to 2019). Heart failure caused by abnormal myocardial contraction during systole leading to defective cardiac emptying. "Experimental and clinical evidence has pinpointed a critical role for matrix metalloproteinase-2 (MMP-2) in ischemic ventricular remodeling and systolic heart failure." (PMID 22509276, 2012).
airway hyperresponsiveness (4 papers, 2019 to 2025). "MMP2 and MMP9 were also described as essential for inflammatory cell infiltration and induction of airway hyperresponsiveness." (PMID 31842927, 2019). "The scarce number of patients, the retrospective nature of the clinical study, the lack of experiments demonstrating that exogenous MMP-2 is also beneficial for lung inflammation and measurement of airway hyperresponsiveness using only enhanced pause are limitations of the current study." (PMID 31428095, 2019).
autoimmune myocarditis (4 papers, 2019 to 2021). Autoimmune myocarditis is an autoimmune disease that affects the heart. "Our current results are also consistent with our previous findings showing that the lowest concentration of CAR was the most effective in inhibiting MMP-2 activity during acute autoimmune myocarditis." (PMID 34959676, 2021). "On the other hand, our study using an autoimmune myocarditis model in BALB/c mice showed that MMP-2, but not MMP-9, is activated in the pathogenesis of DCM, consistent with a previous observation in human DCM27." (PMID 34702968, 2021).
cerebral amyloid angiopathy (4 papers, 2013 to 2022). "On the other hand, GM6001 and another MMP inhibitor, minocycline, were reported to efficiently reduce upregulated MMP-2 and MMP-9 and prevent inflammation and oxidative stress associated with cerebral amyloid angiopathy in AD mice." (PMID 33986628, 2021). "Also, amyloid-β decreases expression of claudin-5, increases activities of MMP-2, -9, causes BBB leakage and promotes BBB permeability in humans with cerebral amyloid angiopathy." (PMID 23505411, 2013). "β-amyloid upregulates MMP-2 expression through the ERK and JNK signaling pathways in brain endothelial cells, which leads to enhanced vascular inflammatory stress and, therefore, cerebral amyloid angiopathy." (PMID 36232390, 2022).
co-infection (4 papers, 2021 to 2025). "In disagreement with our study, serum MMP-2 and MMP-9 and TIMPs in HCV patients were reported either similar to control levels or increased, particularly in those with HCV/HIV co-infection and chronic HBV." (PMID 36551935, 2022). "Thus, MMP-2/TIMP ratios are elevated in TBL-helminth coinfection." (PMID 34350132, 2021).
endometrioid carcinoma (4 papers, 2011 to 2020). "On the contrary, in HGSC and endometrioid carcinoma the frequency of MMP-2 in stroma is almost reduced by half, probably in relation to the malignancy of both subtypes, although this particular distribution is not observed for MMP-9." (PMID 32718331, 2020). "Interestingly, in the analysis by histological subtypes, AR is mainly associated to MMP-2 in HGSC and significantly associated to MMP-9 in endometrioid carcinoma." (PMID 32718331, 2020).